EZH2 (enhancer of zeste 2 polycomb repressive complex 2 subunit)
Diseases named in the same sentence as EZH2 in open-access papers (continued):
Sharing a sentence is not in itself a finding about the gene and the disease.
rhabdoid tumor (39 papers, 2012 to 2026). An aggressive malignant embryonal neoplasm usually occurring during childhood. "On a brighter note, inhibition of the H3K36 demethylase KDM2A was recently demonstrated to rescue resistance to EZH2 inhibition conferred by loss of the H3K36 methyltransferase NSD1 in SMARCB1-deficient rhabdoid tumor cell lines." (PMID 39403928, 2024). "Recent preclinical evidence also supports dual EZH1/2 inhibition over EZH2-selective inhibition for the treatment of malignant rhabdoid tumors with SMARCB1 loss." (PMID 39403928, 2024). "This antagonistic relationship between PRC and SWI/SNF is well illustrated for the SMARCB1 deficient malignant rhabdoid tumour, and EZH2 inhibitors led to regression of malignant rhabdoid tumours in vitro and in vivo." (PMID 38275587, 2023). "Nevertheless, the epigenetic changes to BRM, as well as to p16 and EZH2, are consistent with the low mutation rate observed in Rhabdoid tumors." (PMID 24913006, 2014). "In cancers driven by mutations in the SWI/SNF chromatin remodelling complex, such as rhabdoid sarcoma and small cell carcinoma of the ovary, EZH2 inhibition exploits a specific dependency on PRC2 function, vide infra." (PMID 40181550, 2026). "As explained in section 1, this phenomenon is the mechanistic explanation for why SWI/SNF mutant cancers like rhabdoid tumors have a strong addiction to EZH2, the catalytic subunit of the PRC2 complex." (PMID 40181550, 2026). "Dual inhibition of EZH1/2 is also one of the promising therapeutic approaches for SMARCB1-deficient tumors worth exploring in future clinical practice.EZH1 and EZH2 contribute to the growth of MRT (Malignant Rhabdoid Tumor) cells and H3K27 methylation." (PMID 40115023, 2025). "Clinical trials of EZH2 inhibitors in malignant rhabdoid tumours, small cell carcinoma of hypercalcaemic type, SMARCA4 deficient thoracic sarcoma, and epithelioid sarcoma are ongoing." (PMID 38275587, 2023). "Some studies have demonstrated the efficacy of EZH2 and AURKA inhibitors in patients with rhabdoid tumors, also defined by the loss of SMARCB1." (PMID 35406448, 2022). "The PRC2‐SWI/SNF axis is an important therapeutic target in this tumor and the basis for the use of EZH2 inhibitors in rhabdoid tumor treatment." (PMID 33332735, 2021). "In rhabdoid tumors with SMARCB1 loss-of-function mutations, EZH2 displays a specific dependency which can be exploited using pharmacologic inhibition of EZH2′s enzymatic function." (PMID 33371192, 2020). "SWI/SNF dysfunction has been reported to lead to lost antagonism of Polycomb Repressive complexes in rhabdoid tumors, and such cancers have been found sensitive to inactivation of EZH2 (the catalytic subunit of PRC2)." (PMID 29515757, 2018). "In our initial studies using CRISPR-Cas9 to verify the dependence on EZH2 activity for proliferation of a SMARCB1/SNF5/INI1 mutant malignant rhabdoid tumor (MRT) cell line, we noted that the initial reduction in proliferation was lost over time." (PMID 26578851, 2015). "Pharmacological inhibition of EZH2 by using a new EZH2 inhibitor has been recently shown to induce anti-tumoral effects in malignant rhabdoid tumor (MRT) cells deleted for SMARCB1." (PMID 24575771, 2014). "Further supporting this interplay, loss of RB1 is a mechanism of resistance to EZH2 inhibition in rhabdoid sarcoma; upon RB1 silencing, tazemetostat no longer downregulated CCNA2." (PMID 38405800, 2024). "In our study, the zebrafish embryo model of the rhabdoid tumor sample harboring the typical SMARCB1 deletion and a PRKCD (protein kinase C delta) mutation responded best to the EZH2 inhibitor tazemetostat and the multi-kinase inhibitor ponatinib out of 11 tested drug hits." (PMID 35159116, 2022).
rhabdoid tumor (continued). "In addition to EZH2 histone methyltransferase inhibition, targeting of histone deacetylation has also demonstrated anti-tumor activity for rhabdoid tumors in preclinical studies." (PMID 35159116, 2022). "Interestingly, SCCOHTs, as well as rhabdoid tumors, depend for their survival on the EZH2 mehtyltransferase and, thus, are killed by potent and specific EZH2 inhibitors, such as tazemetostat." (PMID 29389895, 2018). "Of note, EZH2 inhibitors seem to be particularly active in malignant rhabdoid tumors, which are deficient in the Switch/Sucrose NonFermentable (SWI/SNF) chromatin remodeling complexes INI1 (SMARCB1)." (PMID 29575713, 2018). "Alisertib (MLN8237), an Aurora K inhibitor, has shown early evidence of remarkable activity in the treatment of ATRT patients, while CDK, MEK, and EZH2 inhibitors have been shown to be effective in restricting tumor cell growth in rhabdoid tumor cell line and xenograft-based models." (PMID 26646792, 2016). "Finally, EZH2 inhibition induced regression of pediatric rhabdoid tumors, which are almost always dependant on EZH2 activity." (PMID 24367611, 2013). "EZH2 inhibitors induced differentiation and apoptosis in SMARCB1-deleted malignant rhabdoid tumor xenograft." (PMID 38472198, 2024). "Methyltransferase EZH2 is a subunit of PRC2, and inhibition of EZH2 shows regression of malignant rhabdoid tumor xenografts." (PMID 33799327, 2021). "Several other SMARCB1 mutant cancers, including malignant rhabdoid tumors (MRT) and atypical teratoid rhabdoid tumors (ATRT) are candidates for treatment with EZH2 inhibitors." (PMID 34202528, 2021). "Tazemetostat is a potent and highly selective EZH2 inhibitor that has shown antitumor activity in vitro and in SMARCA4-negative malignant rhabdoid tumor of the ovary." (PMID 31996670, 2020). "As such, inhibitors of EZH2 are now being tested in the clinic, and objective responses have been observed in SMARCB1-negative rhabdoid tumors in the setting of a Phase I study." (PMID 27391784, 2016). "Consequently, combined EZH2 and ATR inhibition improved therapeutic responses in diverse patient-derived epithelioid and rhabdoid tumors in vivo." (PMID 40794452, 2025). "EZH2 inhibition alone or in combination with histone deacetylases (HDAC) inhibitors has been suggested for both tumor types, but antagonistic effects of this drug combination on in vitro rhabdoid tumor cell proliferation have also been demonstrated." (PMID 34281526, 2021). "For instance, SMARCB1 (INI1/SNF5/BAF47) is a subunit of the SWI/SNF complex that is lost in nearly all rhabdoid tumors, creating an oncogenic dependency on the PRC2-EZH2 methyltransferase, and sensitizing these tumors to small molecule inhibitors of EZH2 both in vitro and in vivo." (PMID 27391784, 2016). "EZH2 expression has not yet been tested on hepatoblastomas and other primitive "blastic" tumors except Ewing’s sarcoma and rhabdoid tumors which were reported positive." (PMID 22809481, 2012).
small cell lung carcinoma (38 papers, 2013 to 2026). Small cell lung cancer (SCLC) is a highly aggressive malignant neoplasm, accounting for 10-15% of lung cancer cases, characterized byrapid growth, and early metastasis. "In small cell lung cancers, EZH2 overexpression is related to poor prognosis and associated to the H3K27me3-dependent repression of JUB1 in these tumors." (PMID 34991274, 2018). "In addition, EZH2 activity was implicated in chemo-resistance of small cell lung cancers, and epigenetic changes in chemo-resistance were reversible upon EZH2i treatment." (PMID 31704972, 2019). "Inhibition of cell cycle arrest by EZH2 has also been found in other cancers such as cholangiocarcinoma, multiple myeloma, and small-cell lung cancer." (PMID 40028035, 2025). "The combination of EZH2 inhibition together with chemotherapy is presently under investigation in a phase I/II clinical trial involving patients with recurrent small-cell lung cancer (SCLC)." (PMID 39858036, 2025). "An in vivo and in vitro study explores the potential of PROTAC EZH2 degrader‐1 in overcoming chemoresistance in small cell lung cancer (SCLC) with leptomeningeal metastasis (LM)." (PMID 39898116, 2025). "In small-cell lung cancer, the EZH2/H3K27me3 axis silences C–C motif chemokine ligand 2 and suppresses macrophage infiltration, thus promoting tumor development." (PMID 40028035, 2025). "EZH2 is an oncogene with elevated expression in small-cell lung cancer (SCLC) and plays a significant role in SCLC chemoresistance and immune evasion." (PMID 39858036, 2025). "EZH2 influences macrophage infiltration in small-cell lung cancer by mediating H3K27me3 in the enhancer region of CCL2." (PMID 38534385, 2024). "miRNAs with >2‐fold or <0.5‐fold gene expression change by EZH2 siRNA in small cell lung cancer cells." (PMID 39400978, 2024). "Studies on the role of HMT inhibitors in resistance have entered clinical trial phases, with the EZH2 inhibitor EPZ-6438 (Tazemetostat) undergoing trials in platinum-resistant small cell lung cancer patients (Trial ID: NCT05353439)." (PMID 38525426, 2024). "The epigenetic reprogramming and changes in expression are due, in part, to the enhancer of zeste homolog 2 (EZH2), an oncogene that is overexpressed in various cancers including prostate, breast, bladder, endometrial, and small-cell lung cancers." (PMID 38001678, 2023). "Noteworthy, another study found that EZH2 inhibitors prevented emergence of acquired resistance and augmented chemotherapeutic efficacy in both chemosensitive and chemoresistant models of small cell lung cancer." (PMID 36304988, 2022). "The gene body of SLFN11 is also targeted by the histone modifier EZH2 (enhancer of zeste homology 2) during acquired chemoresistance in small-cell lung cancer (SCLC) cells, which increases H3K27me3 and local chromatin condensation." (PMID 35768579, 2022). "EZH2 has been reported to play an important role in the acquired resistance of tumor cells to chemotherapeutic drugs in small-cell lung cancer." (PMID 33276757, 2020). "In small cell lung cancer, EZH2 mediated H3K27me3 suppressed the expression of SLFN11, a factor implicated in DNA-damage repair deficiency, leading to chemoresistance." (PMID 29556394, 2018). "Suppression of EZH2 by use of EZH2 short hairpin RNA up-regulates the pro-apoptotic proteins, Puma and Bad, and enhances p21 protein expression in both non-small-cell and small-cell lung cancers in vitro." (PMID 28561778, 2017). "High expression of EZH2 has been demonstrated in small cell lung cancer, another tumor characterized by hypermethylation of promoter regions." (PMID 26848979, 2016). "Components of polycomb repressive complex 2, including enhancer of zeste 2 (EZH2), were highly expressed in small cell lung cancer cells; this led to epigenetic silencing of TβRII expression and suppression of TGF-β-mediated apoptosis." (PMID 27462425, 2015).
small cell lung carcinoma (continued). "Small cell lung cancer (SCLC) showed high enhancer of zeste homolog 2 (EZH2) expression and promoted epithelial‐mesenchymal transition (EMT), and miR‐4448 prevented EZH2‐mediated EMT and tumorigenesis by modulating the Girdin/Akt/AMP‐activated protein kinase axis." (PMID 39400978, 2024). "SA-β-gal-positive cells represented <4% of the total A549 and H1299 cell population expressing shLuc compared with >10% and 12% of A549 and H1299 cells, respectively, expressing shEZH2, indicating that EZH2 depletion induced cellular senescence in non–small cell lung cancer cells." (PMID 36009484, 2022). "However, inhibition of EZH2 expression or its methyltransferase activity promoted chemosensitivity through the induction of SLFN11 expression in small cell lung cancer, which is contrary to our results in CRC." (PMID 31065671, 2020). "Thus, EZH2 promoted small cell lung cancer progression by suppressing the TGF-β-Smad-ASCL1 pathway." (PMID 27462425, 2015). "By suppressing the TGF-β-Smad-ASCL1 pathway, EZH2 overexpression constricted transforming growth factor-beta (TGF-β)-mediated apoptosis and promoted the progression of small cell lung cancer." (PMID 40028035, 2025). "Depletion of EZH2 led to N-Myc polyubiquitination by SCF-FBXW7, and subsequent N-Myc degradation reduced tumor cell growth in MYCN-amplified NB and small cell lung carcinoma cells." (PMID 37762082, 2023). "In small cell lung cancer cells, SLFN11 expression is silenced by marked deposition of H3K27me3, leading to drug resistance, and is reactivated by inhibition of EZH2 a methyltransferase for H3K27." (PMID 33513156, 2021). "It has been reported that EZH2 promotes chemotherapy resistance by inhibiting Schlafen family member 11 (SLFN11), expression in small cell lung cancer." (PMID 31065671, 2020). "E2F, another cell cycle regulator, positively controls EZH2 transcription through its direct binding on EZH2 promoter upon Rb/RB1 phosphorylation in bladder and small cell lung cancer." (PMID 29556394, 2018). "The Rb-E2F signaling has also been found to activate the expression of EZH2 through direct binding of E2F on the EZH2 promoter upon Rb/RB1 phosphorylation in bladder and small cell lung cancer." (PMID 27793053, 2016). "In small-cell lung cancer (SCLC), overexpressed EZH2 represses CCL2 expression by depositing H3K27me3 at its enhancer, reducing macrophage infiltration into tumors and highlighting EZH2’s role in immune evasion." (PMID 40032852, 2025). "Depleting EZH2, rather than inhibiting its enzymatic activity, results in substantial degradation of Myc, leading to the inhibition of tumor growth in Myc-driven small-cell lung carcinoma and neuroblastoma." (PMID 38534385, 2024). "Moreover, overexpression of JUB1 in small cell lung cancer cells—DMS53, Lul30, and H209 cells—decreased cell proliferation showing that EZH2 promoted lung cancer cell proliferation via the inhibition of JUB1 expression in these models." (PMID 34991274, 2018).
esophageal cancer (36 papers, 2015 to 2025). A primary or metastatic malignant neoplasm involving the esophagus. "Associations have also been reported between EZH2 overexpression and poor prognosis in esophageal cancers, breast cancers, renal cell carcinomas and childhood intracranial ependymoma." (PMID 29221202, 2017). "Studies also confirmed the post-transcriptional regulation mechanisms underlying EZH2 expression and these include miR-101 in gastric, hepatocellular and esophageal cancer." (PMID 29100288, 2017). "Combined hazard ratios suggested that EZH2 overexpression was associated with poor prognosis of OS (HR = 1.54, 95% CI: 1.27–1.81) in patients with oesophageal cancer." (PMID 26859127, 2016). "Combined hazard ratios suggested that EZH2 overexpression was associated with poor prognosis of overall survival (HR = 1.54, 95% CI: 1.27–1.81) in patients with oesophageal cancer." (PMID 26859127, 2016). "We found that EZH2 was associated with distant metastasis in esophageal carcinoma." (PMID 25974088, 2015). "We found that EZH2 levels are significantly upregulated in esophageal cancer tissues compared to normal tissues." (PMID 37171386, 2023). "In esophageal cancer, EZH2, as a histone methyltransferase, promotes esophageal cancer cells' invasion and EMT process by upregulating miR-200c." (PMID 37781524, 2023). "proved that melatonin significantly enhanced 5-FU-mediated suppression of esophageal cancer cell proliferation and migration by regulating enhancer of zeste homolog 2 (EZH2)." (PMID 36591447, 2022). "EZH2 gene can be a beneficial treatment marker for patients with esophageal cancer through decrease invasiveness of the disease and efficient response to neoadjuvant therapy." (PMID 36316365, 2022). "Together, these findings elucidated that TRA2A triggers carcinogenesis via MALAT1 mediated EZH2/β-catenin axis in esophageal cancer cells." (PMID 34234858, 2021). "The results presented here highlights for the first time the relevance of RUNX3 and EZH2 in esophageal cancer, at least in Indian population." (PMID 32943993, 2020). "The observed positive correlation between RUNX3 and EZH2 (p < 0.03) suggests the possibility of their cooperative and/or interactive role in esophageal cancer, which invites further investigation." (PMID 32943993, 2020). "Consistent with our study, oncomine data analysis also revealed RUNX3 and EZH2 up-regulation in five studies on esophageal cancer, OncomineTM (Compendia Bioscience, Ann Arbor, MI) was used for analysis and visualization." (PMID 32943993, 2020). "EZH2 overexpression has been shown in colorectal cancers, esophageal cancers, bladder cancers, and lung cancers." (PMID 29221202, 2017). "Given that MALAT1 modulated Ezh2 expression in esophageal cancer cells, then we examined the expression of Ezh2 in 40 ESCC tissues." (PMID 27015363, 2016). "In this study, we explore the role of SOX4 and EZH2 in miR-31 repression and the contribution of miR-31 to survival, migration and invasion of aggressive esophageal cancers cells." (PMID 25644061, 2015). "In conclusion, EZH2 can be an effective therapeutic marker for esophageal cancer patients." (PMID 36316365, 2022). "However, up-regulation of PSMA3-AS1 significantly increased the expression of EZH2 in esophageal cancer cells." (PMID 32005028, 2020). "When grouped according to the various histological types of digestive cancer, the combined HRs of oesophageal cancer was (HR = 1.54, 95% CI: 1.27–1.81), indicating EZH2 was an indicator of poor prognosis in oesophageal cancer (P = 0.035 for heterogeneity test)." (PMID 26859127, 2016). "Thus, we identified a novel molecular mechanism by which the SOX4, EZH2 and miR-31 circuit promotes tumor progression and potential therapeutic targets for invasive esophageal carcinomas." (PMID 25644061, 2015). "Thus, the detection of EZH2 expression may be of great value in determining the prognosis of oesophageal cancer patients." (PMID 26859127, 2016).